CDK11A (cyclin dependent kinase 11A)
Description:
Cyclin-dependent protein kinase that acts as a regulator of transcription and pre-mRNA splicing. Acts as a key regulator of pre-mRNA splicing by mediating phosphorylation of SF3B1, enabling the association between SF3B1 and U5 and U6 snRNAs in the activated spliceosome, thereby promoting spliceosome assembly. Also acts as a regulator of transcription by phosphorylating 'Ser-2' of the CTD (C-terminal domain) of the large subunit of RNA polymerase II (RNAP II) POLR2A. Involved in replication-dependent transcription of histone genes: binds to histone genes and phosphorylates POLR2A at 'Ser-2' of the CTD to specifically control transcriptional elongation of histones and recruitment of 3'-end processing factors. Part of a transcription checkpoint upstream of CDK9, which regulates promoter-proximal pausing by RNA polymerase II, a transcription halt following transcription initiation, but prior to elongation. Probably regulates promoter-proximal pausing by mediating phosphorylation of POLR2A at 'Ser-2' of the CTD. [Isoform SV6]: Isoform expressed in a non-cell cycle-dependent manner. [Isoform 4]: Isoform specifically expressed during the G2-M phases of the cell cycle. Phosphorylates 'Ser-2' of the CTD (C-terminal domain) of the large subunit of RNA polymerase II (RNAP II) POLR2A. Promotes centromeric transcription to maintain centromeric cohesion during mitosis.
Synonyms: CDC2L2; CDC2L3; PITSLRE; CDK11-p110; CDK11-p58; CDK11-p46; p58GTA
Tractability: Small molecule: a high-quality ligand is known; it belongs to a druggable protein family. PROTAC: it is named in the literature on targeted protein degradation; ubiquitination databases record sites on it; a small molecule that binds it is known.
Target class: Kinase; Enzyme; Protein Kinase; CMGC protein kinase PITSLRE subfamily; CMGC protein kinase group; CMGC protein kinase CDK family
Chemical probes: OTS964 (high quality)
Gene: Protein-coding gene on chromosome 1 (1,702,379 to 1,724,482, reverse strand). Ensembl gene ENSG00000008128.
Subcellular location: Nucleus; Chromosome; Cytoplasm; Nucleus (Isoform SV6); Nucleus (Isoform 4); Chromosome, centromere
Subcellular location (Human Protein Atlas): Nuclear speckles; Cytosol
Pathways (Reactome):
Cell Cycle: Recruitment of mitotic centrosome proteins and complexes
Gene Ontology:
Molecular function: ATP binding; cyclin-dependent protein serine/threonine kinase activity; protein binding; protein serine kinase activity; protein serine/threonine kinase activity; RNA polymerase II CTD heptapeptide repeat kinase activity; RNA polymerase II CTD heptapeptide repeat S2 kinase activity; RNA polymerase II CTD heptapeptide repeat S5 kinase activity; protein kinase activity
Biological process: protein phosphorylation; regulation of cell growth; regulation of mRNA processing; regulation of mRNA splicing, via spliceosome; RNA polymerase II promoter clearance; apoptotic process; mitotic cell cycle; regulation of DNA-templated transcription; regulation of cell cycle; regulation of transcription by RNA polymerase II
Cellular component: chromosome; cyclin L-CDK11 complex; cytoplasm; cytosol; nuclear speck; nucleus; chromosome, centromeric region
Genetic constraint (gnomAD): Loss-of-function variants: 45 observed, 50.18 expected, observed/expected ratio (o/e) 0.9, 90% interval 0.7 to 1.15. The upper end of that interval is the gene's LOEUF score, 1.15, which puts it in group 5 of 6, group 1 being the genes least tolerant of losing a copy. Missense variants: 478 observed, 527.42 expected, observed/expected ratio (o/e) 0.91, 90% interval 0.84 to 0.98. Synonymous variants: 212 observed, 200.47 expected, observed/expected ratio (o/e) 1.06, 90% interval 0.94 to 1.18.
Homologues: Orthologues: macaque CDK11B (98% identical), rat Cdk11b (96% identical), mouse Cdk11b (96% identical), dog CDK11 (91% identical), rat AABR07040938.1 (84% identical), tropical clawed frog cdk11b (82% identical), zebrafish cdk11b (78% identical), Drosophila melanogaster Pitslre (49% identical). Paralogues in human: CDK11B (99% identical), CDK12 (24% identical), CDK13 (24% identical), CDK17 (24% identical), CDK10 (22% identical), CDK16 (22% identical), CDK14 (21% identical), CDK18 (21% identical), CDK15 (19% identical), PRP4K (19% identical), CDK7 (18% identical), CDK2 (18% identical), and 14 more.
Diseases named in the same sentence as CDK11A in open-access papers:
CDK11A is named in the same sentence as 17 diseases in open-access papers, as found by Europe PMC text mining. Sharing a sentence is not in itself a finding about the gene and the disease. The quoted sentences say what the papers report.
breast carcinoma (2 papers, 2015 to 2021). "In contrast, CDK11A mRNA levels were significantly lower in breast cancer tissues than in normal ones." (PMID 33686962, 2021).
melanoma (2 papers, 2015 to 2019). A malignant, usually aggressive tumor composed of atypical, neoplastic melanocytes. "CDK11 mRNA levels were lower in malignant cells compared to primary melanocytes in all of the melanoma cell lines tested, except for CDK11A mRNA in WM39 cells." (PMID 30987032, 2019). "Pathological analysis performed by the Human Protein Atlas for CDK11A in melanoma patients (derived from TCGA) indicates that high CDK11A mRNA expression is an unfavorable prognostic marker." (PMID 30987032, 2019). "CDK11A is a cyclin-dependent kinase with roles in apoptosis and may act as a tumour suppressor in neuroblastoma, melanoma and non-Hodgkin’s lymphoma but may be tumour promoting in osteosarcoma and liposarcoma." (PMID 25969993, 2015). "Gene mutation is not a major component of CDK11A, CDK11B, CCNL1 or CCNL2 function in melanoma." (PMID 30987032, 2019). "It is not surprising that the genes CDK11A and CDK11B and CCNL2, which are all located on chromosome 1p, showed good correlation of expression at the mRNA level in melanoma patient tumor tissues." (PMID 30987032, 2019).
neuroblastoma (2 papers, 2015 to 2018). Neuroblastoma (NB) is the most common solid, extracranial childhood tumor. "Two CDK family genes, CDK11A and CDK11B, are known to play multiple roles in cell cycle progression, cytokinesis and apoptosis, while the gene NBPF1 acts as a tumor suppressor by arresting cell cycle at G1 stage in Neuroblastoma." (PMID 29621297, 2018).
osteosarcoma (2 papers, 2015 to 2016). A usually aggressive malignant bone-forming mesenchymal neoplasm, predominantly affecting adolescents and young adults. "In both osteosarcoma (p = 1.4 × 10−3) and lung cancer models (p = 3.5 × 10−2), we identified an association between mutation/deletion of CDKN2A and dependency upon the cyclin dependent kinase gene CDK11A, which encodes a CDKN2A interacting protein." (PMID 26947069, 2016).
breast tumours (1 paper, 2015). "CDK11A, MME and SEPT6 were also found to altered in 6.2%, 4.5%, and 3.7%, respectively, in a panel of 1062 breast tumours from the Cancer Genome Atlas project, either through mutation, amplification, deletion or altered gene expression." (PMID 25969993, 2015).
cholangiocarcinoma (1 paper, 2021). A carcinoma that arises from the intrahepatic biliary tree (intrahepatic cholangiocarcinoma) or from the junction, or adjacent to the junction, of the right and left hepatic ducts (hilar cholangiocarcinoma). "Additionally, AS events SLC46A1-39899-ES, IARS-86836-ES, and the CDK11A splicing factor may be therapeutic targets for cholangiocarcinoma." (PMID 34055632, 2021). "The CDK11A splicing factor and SLC46A1-39899-ES and IARS-86836-ES AS events may be potential targets for cholangiocarcinoma therapy." (PMID 34055632, 2021).
glaucoma (1 paper, 2022). Increased pressure in the eyeball due to obstruction of the outflow of aqueous humor. "BOD1L1, RALYL, LDB3, ACAD10, CDK11A, and DPF3 are also associated with glaucoma topical treatments (P < 1 × 10−5)." (PMID 36450729, 2022).
hepatocellular carcinoma (1 paper, 2019). A malignant tumor that arises from hepatocytes. "As previously reported, CDK11A is abnormally expressed in penile squamous cell carcinoma and hepatocellular carcinoma." (PMID 30736838, 2019).
Lynch syndrome (1 paper, 2024). An autosomal dominant hereditary neoplastic syndrome characterized by the development of colorectal carcinoma and a high risk of developing endometrial carcinoma, gastric carcinoma, ovarian carcinoma, renal pelvis carcinoma, and small intestinal carcinoma.
tumor (7 papers, 2015 to 2025). "By examining the mutated genes, we found that tumor cells progressively acquired non-synonymous mutations in genes such as KTN1, ALB, APOB, CDK11A, and CDK11B." (PMID 41373592, 2025). "Consistently, previously studies have reported the tumor-promoting anti-cancer effects of CDK11A." (PMID 34055632, 2021). "In the model, ITGA3 and TNFSF10 were identified as risk factors, with high expression adversely affecting the prognosis of PC patients, while CDK11A and RHOG were protective factors, with high expression being favorable for tumor prognosis." (PMID 38956290, 2024).
cancer (4 papers, 2009 to 2021). A tumor composed of atypical neoplastic, often pleomorphic cells that invade other tissues. "For example, TP53BP2, CDK11A, MME and SEPT6 are mutated in MCF10CA1a cells and have strong correlations to a number of cancers." (PMID 25969993, 2015).
CDK11A also shares sentences with these, for which no sentence is quoted: glioma (1 paper); liposarcoma (1); lung carcinoma (1); non-Hodgkin lymphoma (1); penile squamous cell carcinoma (1); tendinopathy (1).